SOX2 (SRY-box transcription factor 2)
Diseases named in the same sentence as SOX2 in open-access papers (continued):
Sharing a sentence is not in itself a finding about the gene and the disease.
tumor (continued). "By contrast, SOX2 haploinsufficiency with decreased functionality of the mutant protein may also be correlated with pituitary tumorigenesis (as observed in human patients), suggesting that SOX2 may also act as tumor suppressor." (PMID 29255445, 2017). "However, as discussed later in the review, there are concerns about the use of tumor cells engineered to stably overexpress SOX2." (PMID 28388544, 2017). "In addition, pituitary SOX2+ cells have been suggested to act as signalling centres, particularly in disease conditions like tumorigenesis in which paracrine signalling from (activated) SOX2+ cells have the capacity to promote tumour development in the gland." (PMID 29208952, 2017). "Third, small changes in the levels of SOX2 alter tumor cell physiology." (PMID 28388544, 2017). "Thus, a larger number of tumor specimens will need to be evaluated to resolve the relationship between miR-126 and SOX2." (PMID 28388544, 2017). "While SOX2 may be acting to protect tumor cells through antiapoptotic signaling or quiescent-like phenotypes, SOX2 may also be promoting drug resistance through various ATP-binding cassette (ABC) transporters, including ABCG2, ABCC3, and ABCC6." (PMID 28388544, 2017). "Knockdown of MALAT1 in each of these tumor cell lines reduced the expression of SOX2." (PMID 28388544, 2017). "To determine whether different expression levels of SEC62 and SOX2 affect tumor cell biology, as indicated by our immunohistochemical analyses, we performed functional analyses using UM-SCC1 cells as an in vitro model." (PMID 28002801, 2017). "However, the specific miR genes regulated by SOX2 are expected to differ widely between tumor cell types due to differences in their transcriptional circuitries." (PMID 28388544, 2017). "This indicates that SOX2 plays an important role in early tumour initiation." (PMID 27343550, 2017). "In addition, SOX2 expression is correlated with small tumor size and early tumor stage, and better disease-free survival." (PMID 28626726, 2017). "We speculate here that different expression levels of Sox2 resulted in different tumorigenic capacity and tumor growth rate." (PMID 29228716, 2017). "Further studies showed that overexpression of HOTAIR could promote tumor sphere formation, which upregulated expression of the tumor stem cell-related biomarkers such as Nanog, Oct3/4, Sox2, c-Myc, β-catenin, and Klf4." (PMID 28978188, 2017). "Hence, clinical and experimental evidences support NFATc2 impedes tumor differentiation and negatively affects patient outcome through coupling to SOX2 in lung AD." (PMID 28737489, 2017). "Notably, accumulating evidence indicates that the expression of oct3/4, nanog, and sox2 transcription factors is strongly correlated with CSCs: knockdown of these genes decreased sphere formation and inhibited tumor development in xenograft tumor models." (PMID 28121625, 2017). "Thus, the effects of SOX2 appear to be highly context-dependent, similar to other genes, notably TGFβ, which can act as a tumor suppressor or oncogene." (PMID 28388544, 2017). "Importantly, Ad-ATF/SOX2 completely inhibited the tumor growth (p = 0.00039 vs Ad-shSOX2 treated group)." (PMID 29262545, 2017). "This is particularly evident for SOX2-positive tumor cell lines." (PMID 28388544, 2017). "The effect of Sox2 on tumor cell invasion and migration was also confirmed ex vivo." (PMID 29228716, 2017). "In addition, SOX2 knockdown also reduces the ratio of tumour/total lung area (10.4% Vs 1.8%) (p < 0.001)." (PMID 28288641, 2017). "This hypothesis was backed by the fact that targeted expression of oncogenic β-catenin in Sox2+ stem/progenitor cells in adult mouse pituitaries gives rise to tumours resembling human aCP46." (PMID 29158570, 2017). "The expression of Sox2 in the tumor tissues was examined by WB and IHC." (PMID 27371094, 2016).
tumor (continued). "We suggest that increases in the levels of SOX2 must be accompanied by corresponding changes in other genes required for growth promotion by SOX2 and/or downregulation of genes that interfere with the action of SOX2 when its levels rise during tumor progression." (PMID 27145457, 2016). "Furthermore, SOX2 inhibition using shRNA halts tumor growth when GBM cells are transplanted into immunodeficient mice." (PMID 27148537, 2016). "Notably, as compared to dysplasia, which had uniformly high SOX2 and P-S6 expression, in 50% of SQCCs, P-S6 expression was observed in 10% or less of tumor cells." (PMID 27880766, 2016). "Similarly, stemness transcription factors, Nanog, Oct4, KLF4, Lin28, and Sox2 were enriched in tumor spheres." (PMID 27259269, 2016). "Moreover, some proteins highly expressed in embryonic stem cells (ESCs), such as PRC2-regulated genes and the transcription factors Klf4, Nanog, Oct4, and Sox2, are frequently present in poorly differentiated tumours with adverse clinical outcome." (PMID 27766946, 2016). "When we counted the cells in the immunofluorescent images of the tumor tissues around necrotic areas, SOX2+ HIF-1α+ RNApII-S2P-/low cells and NANOG+ HIF-1α+ RNApII-S2P-/low cells accounted for 0–6.3% and 0–4.7% of the cells in the microscopic field, respectively." (PMID 26799577, 2016). "In the present study, by combining clinical sample analyses with in vitro experiments, we characterized a niche harboring quiescent stem-like tumor cells of the SOX2+ HIF-1α+ RNApII-S2P-/low or NANOG+ HIF-1α+ RNApII-S2P-/low phenotypes, which are associated with an enhanced tumorigenic capacity." (PMID 26799577, 2016). "These resulting tumor‐derived spheres express markers associated with stemness (e.g., Nestin, SOX2, SCA1, and CD133) and do not express differentiation markers (e.g., growth hormone)." (PMID 26763580, 2016). "The transcription factors SOX2 and OCT4 normally drive the pluripotency of embryonic stem cells but have now been implicated in maintaining cancer stem cells, which may serve as tumor-initiating cells for a large number of tumors." (PMID 26800519, 2016). "SOX21 in combination with SOX2 exerts a tumor-suppressive effect on carcinogenesis." (PMID 27933111, 2016). "However, an increase in SOX2 expression was observed in the Fuji xenograft at the highest dose, a dose at which tumor stasis was observed." (PMID 27391784, 2016). "Interestingly, we also find that Sox2 is critical in metastatic dynamics at secondary sites, as the number of disseminated tumor foci at various body parts depends on Sox2." (PMID 26787224, 2016). "In IHC, multivariate analyses demonstrated that Lgr5, CD133 and EpCAM were independently related to old age, CD133 and Sox2 were independently associated with well or moderate differentiation, while Oct4, CD133 and EpCAM were independently related to tumor progression." (PMID 27557490, 2016). "Surprisingly, SOX2 copy number deletions were detected in a subset of tumor samples in this cohort." (PMID 26780934, 2016). "Thus, We guessed that ZEB2 induced tumor stemness through modulating miR-200/BMI1/SOX2 signals in NPC." (PMID 27589832, 2016). "However, to a large extend the overall levels in tumor core in patients and mice were similar, except for musashi-1 and sox-2 which were expressed at much higher or higher levels in both core and periphery in patients GBMs compared to GBM xenografts." (PMID 27171431, 2016). "Interestingly, a combination therapy with PDGF and IGF1 receptor inhibitors (imatinib and NVP-AEW541) produces a significant tumor growth reduction through SOX2 downregulation and GSC sensitization." (PMID 27822457, 2016).
tumor (continued). "Here, in order to identify highly consensus SOX2 downstream genes in lung SCC cells, we used RNA-seq data from 178 lung SCC specimens (containing tumor and tumor-associated cells) and analyzed the correlation between SOX2 and previously-reported SOX2-controlled genes in lung SCC." (PMID 26846300, 2016). "However, different results are obtained when tumor cells are engineered for inducible overexpression of SOX2." (PMID 27145457, 2016). "RGD-peptide treatment of mice with established intracerebral GBM xenografts significantly reduced the percentage of Sox2-positive tumor cells and CSCs in close proximity to ECs, decreased integrin αvβ3 and BMX activation and p130CAS phosphorylation in the ECs, and reduced the vessel surface area." (PMID 27270311, 2016). "These HA/CD44-activated signaling regulators (PKCε, JNK, c-Src, Nanog, Stat-3, c-Jun, Oct4, Sox2 and Twist), together with various miRNAs could be used as structure/function-related tumor markers for human cancer detection and prognosis." (PMID 27070574, 2016). "Moreover, treatment with AKT inhibitors was able to fully suppress tumor formation while, in agreement with our in vitro findings, induction of SOX2 expression was able to partially restore tumor formation inspite of AKT inhibition." (PMID 26498353, 2015). "It was also noteworthy that mRNA Sox2 was increased 11.77 fold in the tumor tissues." (PMID 26159226, 2015). "These groups allowed us to investigate whether the tumor growth inhibition mediated by SOX2 methylation was stably transmitted even after removal of ZF598-DNMT3A expression." (PMID 25684141, 2015). "Unlike other canine oSCCs, tumor 1172 overexpresses the pluripotent marker SOX2 and at least 20 homeobox genes that are associated with embryonic morphogenesis, but does not express EMT markers in many of its tumor cells." (PMID 26030765, 2015). "Class III β-tubulin, Sox2, and Survivin play important roles in tumor survival and proliferation." (PMID 26198101, 2015). "The function of SOX2 has also been specifically characterized in GBM tumor-initiating cells." (PMID 26258069, 2015). "Furthermore, de novo DNAme was stably maintained in vivo even 53 days after removal of the ZF598-DNMT3A and was accompanied with a sustained suppression of SOX2 expression and tumor growth inhibition." (PMID 25684141, 2015). "Additional studies indicated that the GSC marker SOX2 is necessary to initiate tumor growth." (PMID 26167936, 2015). "Tumor cells expressing high levels of Sox2 represent undifferentiated tumor cells." (PMID 26444992, 2015). "It is puzzling that mutated SOX2+ve stem cells in the adult pituitary are not the cell of origin of the tumours in the mouse as it would be expected according to the CSC paradigm." (PMID 25611703, 2015). "Msi1, ALDH1, and Sox2 expression were positively correlated with tumor recurrence (P = 0.005, P = 0.003, and P = 0.003, respectively), while CD49f expression was negatively correlated with tumor recurrence (P = 0.028)." (PMID 26499463, 2015). "If murine ACP tumours are not derived from the mutated SOX2+ve stem cells in a cell‐autonomous manner, what is the mechanism underlying tumour formation?" (PMID 25611703, 2015). "Furthermore, the expression of cancer stem cell markers like c-Met, Sox2, Oct-4 were also decreased in the tumor with salinomycin treatment compared to those from control group." (PMID 25483103, 2015). "Using mRNA and protein expression analysis, luciferase assays and rescue assays, they demonstrated that restored expression of Sox2 dampened miR-126-mediated suppression of tumor progression, which suggested the important role of miR-126/Sox2 interaction in tumor progression." (PMID 26194657, 2015).
tumor (continued). "Therefore, the function of the SOX2 gene in abnormally differentiated tumor tissues has become of particular interest." (PMID 25663891, 2015). "They found the down-regulation of SOX2 by siRNA abrogated completely the tumorigenicity further suggesting this transcription factor regulates the expression of key genes and pathways that control tumor initiation and progression." (PMID 26452033, 2015). "Concordantly, in 13% of the cases SOX2 expression was higher in the tumor invasive front." (PMID 25300947, 2014). "SOX2 protein expression was observed in tumor tissue in 89% of patients." (PMID 24940116, 2014). "The fact that several tumors have very low numbers of such cells suggests that SOX2 expressing cells could have been eliminated over the course of disease, which is in support of active tumor immune-surveillance and immune-editing in these patients." (PMID 24940116, 2014). "In many of these tumor types, Sox2 was found in the cancer stem-like cell population." (PMID 24885403, 2014). "We speculate that SOX2 gene gain is an early event in lung tumorigenesis and that tumor progression leads to additional molecular abnormalities that affect patient outcome." (PMID 24736592, 2014). "SOX2 seropositivity showed a significant association with the intensity of SOX2 staining in the tumor (p = 0.02) but not with the frequency of SOX2 expressing cells." (PMID 24940116, 2014). "The intra and inter-tumor heterogeneity for the amplification of TERC/SOX2 locus was observed." (PMID 24410919, 2014). "Interestingly, SOX2 has been coined as a lineage-survival oncogene in different tumor models, proposing that cell lineage–specific genes involved in development can become dysregulated in cancer and promote tumorigenesis." (PMID 25300947, 2014). "Furthermore, studies performed on NPC tumor biopsies or cell lines with enhanced invasiveness or epithelial-mesenchymal transitions also revealed enhanced expression of Sox2, Oct-4, and Nanog, similar to the findings reported here on CD24+ cells." (PMID 24955581, 2014). "Therefore, bovine oocyte extract generates different epigenetic reprogramming effects on tumour suppressor genes and the oncogenic pluripotency gene SOX2." (PMID 24889513, 2014). "Taken together, these findings suggest that Sox2 expression in primary ER-positive tumours may be a clinical prognostic biomarker for tamoxifen resistance." (PMID 24178749, 2014). "In addition, abnormal expression of SOX2 has been observed in tumors of the brain, breast, lung and esophagus." (PMID 25300947, 2014). "Furthermore, the SOX2 expression levels in the tumor tissues were inversely correlated with TNM stage." (PMID 24885288, 2014). "SOX2 proved to be an independent prognostic factor and notably SOX2 expression increased the risk of recurrence by 3 times (HR= 2.98; 95% CI 1.40-6.30; p=0.004), irrespective of tumor size, nodal involvement and endocrine receptors." (PMID 25127259, 2014). "Indeed, SOX2 down-regulation in BC cell lines resulted in decreased tumor cell proliferation and colony formation." (PMID 25127259, 2014). "Intriguingly, increased Sox2 levels also significantly correlated with lower PR expression than in primary tumours, as observed in the resistance models examined, suggesting that the ER signalling pathway is compromised during development of tamoxifen resistance." (PMID 24178749, 2014). "In CRC it has also been suggested that the expression of SOX2 can predict tumor metastasis." (PMID 25010701, 2014). "Furthermore, the Sox2 protein was detected by immunohistochemical staining in tumor xenograft tissues formed by EGFP-positive and EGFP-negative SiHa and C33A cells." (PMID 24489842, 2014). "The present study was designed to detect hTERC and SOX2 amplifications in OSSC exfoliative tumor cells and evaluate whether those two gene amplifications might serve as a supportive biomarker in early detection and diagnosis of oral and oropharyngeal SCC." (PMID 24410919, 2014).
tumor (continued). "As SOX2 often were expressed in a limited part of the tumor, we speculate that these cells might be representing the cancer stem cell niche in these particular tumors." (PMID 25010701, 2014). "IHC confirmed SOX2 protein expression in both tumor tissue from study and control patients." (PMID 25340937, 2014). "Additionally, we also observed a significant (>40%) downregulation of OCT4 and SOX2 at the mRNA level following the knockdown of DCLK1 in AsPC-1 tumor xenografts." (PMID 24040120, 2013). "The mean Sox2 and Lin28 expression levels in the 28 cases with a large tumor size (>5 cm) were 3.79±0.29 and 4.66±0.40, respectively; whereas in the 29 cases with a small tumor size, the levels were 2.79±0.29 and 3.55±0.31 (P=0.02 and 0.03), respectively." (PMID 23599755, 2013). "SP cells exhibited greater tumor-initiating ability and higher expression levels of iPS cell-related genes (SOX2, POU5F1 and NANOG), indicating that SP cells derived from LHK2, SW480 and MCF7 cells are enriched with CSCs/CICs and are a reasonable source for further research." (PMID 24244262, 2013). "What is the composition of the SOX2-interactome in the MB tumor cell line DAOY?" (PMID 23667531, 2013). "First, Sox2-positive tumors may confer a worse overall disease prognosis thus implicating positive Sox2 tumor expression as a potential biomarker for discerning poor prognosis tumors." (PMID 23326489, 2013). "Moreover, spheroid-selected A431 cells express increased levels of stem cell markers, including Bmi-1, Sox2, Ezh2 and H3K27me3, and spheroid-selected A431 cells are highly efficient tumor forming cells." (PMID 24376802, 2013). "Furthermore, our results also revealed that the high expression of SOX2, OCT4 and Nanog was closely associated with tumor aggressive behaviors of NPC patients." (PMID 23424657, 2013). "In order to assess the prognostic value of SOX2 amplification on the clinical course of disease in sinonasal SCCs, INVCs and SNUCs, we correlated the SOX2 amplification status with the incidence of tumor recurrence." (PMID 23544055, 2013). "In contrast, mRNA expression of SOX2 remained unchanged in both tumor cell lines." (PMID 23969837, 2013). "Mean SOX2 expression levels were comparable in metastatic versus primary tumor tissues." (PMID 23544055, 2013). "Lo KW and co-workers have recently demonstrated that CD44 and SOX2 expression are enriched in C666-1 tumor sphere forming cells which may serve as the potential candidate stem cell markers for the NPC C666-1 cells." (PMID 24156782, 2013). "Oppositely, NANOG-knockdown cells generated tiny tumor nodules with lower levels of SOX2 and MUC1." (PMID 23662114, 2013). "Sox2 has also been shown to be a marker of malignancy and is important in tumor cell progression." (PMID 24137328, 2013). "Since SOX2 protein expression levels were higher in SCCs, SNUCs and INVCs compared to ADs and ACCs regardless SOX2 gene copy number status, we hypothesize that SOX2 plays a more important role in these 3 tumor entities." (PMID 23544055, 2013). "It is hypothesized that the Sox2 protein plays a pivotal role in the proliferation and invasion capacity of tumor cells." (PMID 23251245, 2013). "Indeed, ectopic expression of lentiviral Sox2 was sufficient to significantly increase LAPC-4 tumor formation in castrated male nude hosts." (PMID 23326489, 2013). "To determine whether Sox2 overexpression suppresses tumor growth in vivo, we examined xenograft tumor growth in athymic nude mice." (PMID 23451179, 2013). "Thus, we screened for changes in SOX17 and SOX2 expression as an indicator of a successful transition of TCam-2 cells to an EC-like tumor." (PMID 24386123, 2013).